RPS15AP12 (ribosomal protein S15a pseudogene 12)
Synonyms: RPS15A_5_166
Gene: Processed pseudogene on chromosome 1 (220,143,964 to 220,144,351, reverse strand). Ensembl gene ENSG00000232134.
Diseases named in the same sentence as RPS15AP12 in open-access papers:
RPS15AP12 is named in the same sentence as 2 diseases in open-access papers, as found by Europe PMC text mining. Sharing a sentence is not in itself a finding about the gene and the disease. The quoted sentences say what the papers report.
ovarian carcinoma (1 paper, 2025). A malignant neoplasm originating from the surface ovarian epithelium. "RPS15AP12 enhances the growth ability and metastatic capabilities of ovarian cancer (OC) cells via functioning as a competitive endogenous RNA (ceRNA) for its host gene, RPS15A, through the sequestration of miR‐96‐3p." (PMID 40000433, 2025). "The RPS15AP12/ RPS15A axis exhibits an anti‐tumour effect via inhibiting innate immune response in ovarian cancer." (PMID 40000433, 2025).
tumour (1 paper, 2025). "Using a subcutaneous xenograft model and a peritoneal metastasis model, we observed that depletion of RPS15AP12 substantially reduced subcutaneous xenograft formation both in volume and weight by OC cells, as well as the metastasis of xenograft tumours." (PMID 40000433, 2025). "Tumour promotion role of RPS15AP12 and its cognate parent gene was characterized by cell proliferation, transwell assays, and scratch assays in ovarian cells and xenograft nude mice." (PMID 40000433, 2025). "By utilizing integrative RNA‐seq, we found that blocking the RPS15AP12/miR‐96‐3p/RPS15A axis had an anti‐tumour effect via innate immune responses, as it decreased OC cell proliferation, increased the expression of RNA sensors RIG‐I and MDA‐5, and activated the downstream type I IFN pathway." (PMID 40000433, 2025). "RPS15AP12‐lncRNA, regulated by m6A, competes with RPS15A for miR‐96‐3p binding, thereby inhibiting innate immune pathways and facilitating tumour progression." (PMID 40000433, 2025). "Importantly, the deletion of RPS15AP12 diminishes the expression of RPS15A, leading to the upregulation of anti‐tumour immune responses by activating RIG‐I and MDA5 and downstream p‐TBK1 and p‐IRF3 as well as IFN‐β levels." (PMID 40000433, 2025).